APOE (apolipoprotein E)
Diseases named in the same sentence as APOE in open-access papers (continued):
Sharing a sentence is not in itself a finding about the gene and the disease.
insomnia (15 papers, 2016 to 2025). A sleep disorder characterized by difficulty in falling asleep and/or remaining asleep. "The APOE ε4 genotype notably enhances the pathogenic effect of insomnia on AD risk, emphasizing the crucial role of gene-environment interactions in the disease process." (PMID 40264463, 2025). "For example, MR studies provided causal evidence supporting the hypothesis that “insomnia accelerates AD progression through oxidative stress” and identified the enhanced pathogenic effect of insomnia in individuals with the APOE ε4 genotype." (PMID 40264463, 2025). "Voxel-based morphometry and tract-based spatial statistics were used to assess between-group differences and potential interactions between insomnia and the APOE genotype in gray matter volume and white matter diffusion metrics." (PMID 31907066, 2020). "Our interaction analyses point to APOE as a potential modulator in the association between sleep and brain structure, with a higher detrimental effect of insomnia on brain structure being observed among APOE-ɛ4 carriers." (PMID 31907066, 2020). "Wang & Lung demonstrated that both APOE ε4 and PGC-1α polymorphisms increase insomnia risk, and that the effect of PGC-1α remains even after controlling for APOE ε4 status." (PMID 27999387, 2016). "Interestingly, of 554 risk loci for insomnia identified thus far, this locus is among only three loci that colocalize with CVD (pp>0.90; others include the APOE region and LINGO4/RORC)." (PMID 40176577, 2025). "The regression model controlled for age, sleep characteristics including chronotype and report of insomnia, obstructive sleep apnoea traits (daytime sleepiness and snoring) as well as vascular co-morbidity, smoking, BMI, APOE ε4 genotype and socioeconomic status." (PMID 35241774, 2022). "Additionally, cognitively healthy APOE ε4 carriers had lower gray matter volume if they suffered from insomnia." (PMID 34408639, 2021). "VBM analyses returned a significant interaction between insomnia and APOE-ε4 status in several gray matter regions including the left angular, left middle temporal, bilateral superior frontal, left fusiform, and bilateral postcentral gyri, as well as the thalami and the right hippocampus." (PMID 31907066, 2020). "Conversely, non-recallers were more likely to have maintenance insomnia, and to be an APOE e4 carrier or current smoker; they were also older and had higher p-tau217 levels." (PMID 41001478, 2025). "On the other hand, we also found that APOE-ɛ4 carriers without insomnia tend to display higher gray matter volumes compared with non-carriers, which was not expected." (PMID 31907066, 2020). "In these regions, divergent structural patterns were observed among individuals with different APOE-ε4 status depending on the presence or absence of insomnia." (PMID 31907066, 2020). "Multivariable regression models were used to evaluate differences in cognitive performance between individuals with and without insomnia, as well as potential interactions between insomnia and the APOE genotype." (PMID 31907066, 2020). "APOE-ε4 homozygotes had a lower prevalence of insomnia (26.7%), compared with heterozygotes (37.7%) and non-carriers (36.6%), although this difference was not statistically significant and could be explained by the homozygous younger mean age." (PMID 31907066, 2020). "In addition, we found that the association between insomnia and gray matter volume is modulated by the APOE-ε4 status, so that APOE-ε4 carriers tend to display lower gray matter volumes in the presence of insomnia, but higher volumes when insomnia is not present." (PMID 31907066, 2020).
osteoporosis (15 papers, 2010 to 2026). A condition of reduced bone mass, with decreased cortical thickness and a decrease in the number and size of the trabeculae of cancellous bone (but normal chemical composition), resulting in increased fracture incidence. "Lastly, we show that our models can pick up known associations with HLD through APOE, and identify a lesser-known association with osteoporosis through MS4A6A that may be female specific." (PMID 38383858, 2024). "The polymorphic gene Apolipoprotein E (ApoE), with three common alleles (ε2, ε3, ε4) coding for three isoforms (E2, E3, E4), might play a role in osteoporosis." (PMID 35163424, 2022). "Most studies demonstrated that high-fat or high-cholesterol diets induced osteoporosis in ApoE−/− mice." (PMID 37091976, 2023). "Vitamin D receptor (VDR), Type I collagen (COL1), estrogen receptor (ER), apolipoprotein E (ApoE), bone morphogenetic protein (BMP), LRP5 genes and polymorphisms have been also proved to be involved in osteoporosis etiology." (PMID 31113874, 2019). "Second, the two-year follow-up period may be too short to reveal a significant relationship between LTL attrition and other factors (such as osteoporosis and APOE ε4 carrier status), and the number of patients was small." (PMID 35366243, 2022). "Treatment of Western diet-fed ovariectomized ApoE−/− mice (presenting both advanced atherosclerotic calcification and osteoporosis) with E2 inhibited osteoporosis and the BMP osteogenic pathways in aortas by decreasing SMAD1/5/8 phosphorylation, thus leading to reduction in calcium accumulation." (PMID 34204304, 2021). "However, future work investigating the efficacy of using ApoE-neutralizing antibodies to treat osteoporosis may shed light on this anomaly." (PMID 41571629, 2026). "One study showed, in mice lacking ApoE, increased bone formation, which was attributed to the decreased uptake of triglyceride-rich lipoproteins by the OBs, indicating that ApoE is also a risk factor for osteoporosis." (PMID 36836731, 2023). "The development of VC and osteoporosis was evaluated after AD feeding for 13 weeks in KP-treated ApoE−/− mice and compared to C57BL/6 and ApoE−/− mice fed a standard chow diet (CD)." (PMID 37091976, 2023). "For example, the vitamin D receptor (VDR), collagen type I (COL1), estrogen receptor (ER), apolypoprotein Е (ApoE), bone morphogenetic protein (BMP), and Low-density lipoprotein receptor-related protein 5 (LRP5) are all involved in the pathogenesis of osteoporosis." (PMID 38098042, 2023).
papillary thyroid cancer (15 papers, 2021 to 2025). "APOE suppresses ferroptosis in papillary thyroid carcinoma (PTC) via the PI3K/AKT1 pathway, elevating GPX4/FTH1 expression while reducing Fe2+ accumulation." (PMID 41390817, 2025). "Another study suggested that FTO suppressed glycolysis and growth of papillary thyroid cancer via decreasing stability of APOE mRNA in an m6A dependent manner." (PMID 37840133, 2023). "In thyroid papillary carcinoma, apolipoprotein E (APOE) induces the expression of GLUT1 and other glycolytic enzymes through the IL-6/JAK2/STAT3 signal pathway to promote the genesis and development of cancer." (PMID 37582735, 2023). "Surprisingly, CLU and APOE expression showed strong relationships with the prognosis of patients with papillary thyroid cancer." (PMID 33521130, 2021). "CLU and APOE are involved in the molecular mechanism of papillary thyroid cancer." (PMID 33521130, 2021). "However, the clinical value of APOE in papillary thyroid carcinoma (PTC) remains to be determined." (PMID 35371313, 2022). "FTO catalyzes m6A demethylation of Apolipoprotein E (APOE) mRNA, which is subsequently bound and stabilized by IGF2BP2, thereby suppressing glycolysis in papillary thyroid cancer through modulation of the IL-6/STAT3 signaling cascade." (PMID 40986143, 2025). "IGF2BP2 recognizes and upregulates m6A-modified Apolipoprotein E (APOE), promoting glycolysis and tumor growth in papillary thyroid cancer." (PMID 39596216, 2024). "In papillary thyroid cancer, low expression of FTO upregulates m6A methylation of apolipoprotein E (APOE) mRNA, modulating the IL-6/JAK2/STAT3 pathway, thus promoting tumor glycolysis and growth." (PMID 39695216, 2024). "We found that APOE and CLU were the hub genes regulating proliferation and invasion through the extracellular matrix in papillary thyroid cancer." (PMID 33521130, 2021). "However, in papillary thyroid cancer, FTO acts as a tumor suppressor to inhibit APOE expression and hinder glycolysis via the IL-6/JAK2/STAT3 signaling pathway." (PMID 41184232, 2025). "However, FTO can erase the m6A modification level of APOE mRNA, reduce its binding with IGF2BP2 and reduce its stability, and ultimately inhibit the glycolysis and proliferation of thyroid papillary carcinoma." (PMID 37582735, 2023). "Moreover, IGF2BP2 recognizes and upregulates m6A-decorated Apolipoprotein E (APOE) to promote glycolysis and tumor growth in papillary thyroid cancer." (PMID 37554271, 2023).
astrocytoma (14 papers, 2009 to 2024). "Previous work using a human astrocytoma cell line identified a PPAR response element (PPRE) in a similar region (downstream of APOE and upstream of APOC1) that was important in driving macrophage expression of APOE." (PMID 34878094, 2022). "Utilizing annotated chemical libraries and a phenotypic screening strategy that measured apoE secretion from a human astrocytoma cell line, inhibition of pan class I histone deacetylases (HDACs) was identified as a mechanism to increase apoE secretion." (PMID 29579087, 2018). "The level of apoE secreted into media by a human astrocytoma cell line (CCF-STTG1) was measured following exposure to compounds from several annotated chemical libraries including a focused library from the Pfizer compound collection (chemogenomics library)." (PMID 29579087, 2018). "We performed a high-throughput screen using a library of 104,000 small molecules to identify compounds that increase apoE secretion from human CCF-STTG1 astrocytoma cells." (PMID 27598782, 2016). "We confirmed the CCF-STTG1 astrocytoma cell findings in primary human astrocytes, where we observed a robust induction of both apoE and ABCA1." (PMID 27598782, 2016). "Of these, 610 shows weak ability to increase ApoE from human astrocytoma cells (CCF-STTG1) at a concentration of 40 μM." (PMID 26133553, 2015). "A high-throughput phenotypic screen was conducted using a CCF-STTG1 human astrocytoma cell line to identify small molecules that could upregulate apoE secretion." (PMID 32366277, 2020). "An additional correlation between the effect of these two neuroprotective agents comes from the evidence that guanosine may increase cholesterol efflux from astrocytes and rat astrocytoma and increase expression of apolipoprotein E (ApoE) in astrocytes." (PMID 27699087, 2016). "Among these compounds, Aplysamine-1 significantly modulates apolipoprotein E (ApoE) and doubles its secretion from human CCF-STTG1 astrocytoma cells at a concentration of 30 μM." (PMID 38864445, 2024). "Our data support compound 82879 as a robust inducer of apoE and ABCA1 that validates across two human astrocytic cell types, including CCF-STTG1 astrocytoma cells and more physiologically relevant primary astrocytes from three distinct donors." (PMID 27598782, 2016). "Several of these genes, including MYC, EGFR, HIF1A, HGF, APOE, TIMP3, and WNT5A have been identified as being important to development of astrocytoma." (PMID 23737970, 2013). "In cultured human astrocytoma cells (CCF-STTG1), both haloperidol and clozapine significantly up-regulated ApoE, NPC1 and NPC2 at 24 hours of incubation (n = 3)." (PMID 19715613, 2009). "To better understand the mechanisms of apoE regulation, as well as the potential therapeutic utility of promoting apoE lipidation, we performed a focused phenotypic screen to identify small molecules that increase apoE secretion from human CCF-STTG1 astrocytoma cells." (PMID 32366277, 2020). "Upon T1317 treatment, the CCF-STTG1 human astrocytoma cell line released cholesterol to exogenously added HEK-apoE3 conditioned media but not to HEK-control vector conditioned media suggesting that apoE is a putative acceptor for ABCA1-mediated cholesterol efflux stimulated by LXR agonists." (PMID 21034469, 2010). "Cholesterol-loaded CCF-STTG1 astrocytoma cells were treated with approximately 50 μg/ml of apoE3-concentrated media or the equivalent of total protein from vector-concentrated media/ml (no detectable apoE) plus 5 μM T1317 or vehicle, and incubated in serum-free media for 48 hours." (PMID 21034469, 2010). "To extend our studies beyond CCF-STTG1 astrocytoma cells (APOE3/APOE4), we next verified the apoE and ABCA1 activities of compound 82879 in non-transformed primary human astrocytes from three donors genotyped as APOE3/E3 or APOE3/E4." (PMID 27598782, 2016).
Atherosclerotic lesion (14 papers, 2011 to 2026). A lesion associated with atherosclerosis, a multifactorial and multipart progressive disease manifested by the focal development within the arterial wall of lesions, that ranges from the development of a fatty streak, plaque progression, and plaque disruption. "Finally, IL-1β-regulated T-cells, which also promote neutrophil recruitment, and total immune cell counts in atherosclerotic lesions were also significantly less in ApoE/PR3/NE-deficient mice than ApoE-deficient controls." (PMID 38535096, 2024). "Following crosslinking with multi-arm PEG for in situ gelation, aVD-loaded FM-depots maintained high levels of Foxp3+ Tregs in both lymphoid organs and atherosclerotic lesions for weeks following a single subcutaneous injection into ApoE−/− mice." (PMID 32582667, 2020). "After feeding with a high-fat diet for fourteen weeks, the ApoE-/- fat-1 transgenic mouse was found to have fewer atherosclerotic lesions than the ApoE-/- mouse." (PMID 31066787, 2019). "To further validate these results, we investigated the expression levels of ABI3 in macrophages of advanced atherosclerotic lesions in vivo, ApoE−/− mice were fed with a high-methionine diet for 4 or 18 weeks to induce early or advanced atherosclerotic lesions as reported." (PMID 38062164, 2024). "A possible explanation to these sex-specific changes in pathologies might be due to female ApoE (−/−) mice developing atherosclerotic lesions and plaques faster than the male mice, thus the disease progression, and therefore the response to both housing and WS might differ by sex in this model." (PMID 38659910, 2024).
brain tumor (14 papers, 2016 to 2026). "Authors concluded that ApoE polymorphisms may increase vulnerability of patients with brain tumor to cognitive dysfunctions related to treatments." (PMID 27493954, 2016). "This study is the first demonstration that activated astrocytes with strong GFAP signals were the primary cells responsible for the APOE production at the brain tumor edge." (PMID 40745073, 2026). "In summary, we have shown that astrocytes drive the accumulation of apolipoprotein E at the brain tumor edge." (PMID 40745073, 2026). "The spatially distinct correlation of APOE with both macrophages and astrocytes in brain tumors also suggests the different metabolic microenvironments and regulatory mechanisms within and around the tumor." (PMID 40745073, 2026). "The ApoE decoration enhances circulation time in the bloodstream and facilitates targeted delivery to brain tumors by interacting with receptors overexpressed on both BBB endothelial cells and GBM cells." (PMID 41002535, 2025). "ELISA confirmed that LIGHT was successfully secreted in brain tumors, and the expression level in Nano-reshaper group was also higher than in ApoE-pLIGHT@CaP group, suggesting encapsulated CP improved the transfection efficiency." (PMID 36702831, 2023). "These brain tumor edge-associated astrocytes are responsible for the accumulation of APOE in this region and create a unique metabolic environment, which may contribute to brain tumor invasion and resistance to therapy." (PMID 40745073, 2026). "Future studies of knocking down the APOE in the astrocyte may help to uncover their role in brain tumor progression." (PMID 40745073, 2026). "The formation of the ApoE-enriched protein corona significantly improved the cellular uptake of Aβ-CN-PMs on C6 cells and human umbilical vein endothelial cells (HUVECs) and enhanced permeability to the blood–brain tumor barrier in vitro." (PMID 34963449, 2021). "Similarly, APOE-mediated lipid transport may represent a new therapeutic target in brain tumors." (PMID 39530009, 2024). "As ApoE-CaCP efficiently increased CD8+ and CD4+ T cells in blood circulation, we continued to analyze T-cell infiltration in brain tumors." (PMID 36702831, 2023). "The ApoE modification facilitated BBB penetration and tumor cell uptake via interactions with low-density lipoprotein receptors, which are overexpressed in both U87MG brain tumor cells and BBB endothelial cells." (PMID 41002535, 2025). "Collectively, these results suggested ApoE-CaCP alleviated lymphopenia and the optimum dose of CP in vivo application was 10 mg/kg, but ApoE-CaCP still failed to increase T-cell infiltration in brain tumors." (PMID 36702831, 2023). "We found that though systemic immune function was enhanced to increase circulated T cells after the treatment of ApoE-CaCP, effector T cells were not significantly increased in brain tumors, indicating the existence of disrupted local immune function." (PMID 36702831, 2023).
Cirrhosis (14 papers, 2016 to 2025). A chronic disorder of the liver in which liver tissue becomes scarred and is partially replaced by regenerative nodules and fibrotic tissue resulting in loss of liver function. "Among the 20 NAFL and cirrhosis variants, only p.Cys130Arg in APOE and p.His48Arg in ADH1B were associated with BMI (nBMI measures = 486, 305)." (PMID 36280732, 2022). "The rs429358:C allele (APOE) was significantly less frequent in HCC cases versus cirrhosis controls (OR, 0.71; 95% confidence interval [CI], 0.61‐0.84; P = 2.9 × 10−5)." (PMID 34958182, 2022). "Similarly, the rs429358:C allele in APOE is associated with higher FIB‐4 values (implying a higher risk of cirrhosis) but is associated with a lower risk of cirrhosis." (PMID 39425533, 2024). "The lead variants at PNPLA3, TM6SF2, and APOE were either coding or in high LD with a coding variant and have all been previously implicated in the full spectrum of MASLD, including cirrhosis and HCC." (PMID 40823170, 2025). "These variants, including single nucleotide polymorphisms (SNPs) in MARC1, APOE, and GPAM, were all additionally associated with chronic liver disease and cirrhosis." (PMID 34950105, 2021). "The persistence of this association when comparing against cirrhosis controls strongly implies that APOE has a direct role in liver carcinogenesis and does not simply reduce HCC by altering progression to cirrhosis." (PMID 34958182, 2022). "Furthermore, a global correlation map of clinical and proteomic data strongly associated DPP4, ANPEP, TGFBI, PIGR, and APOE with NAFLD and cirrhosis." (PMID 30824564, 2019). "According to our previous network analysis of differentially expressed proteins in cirrhosis serum based on literatures, APOA1 and APOE have been introduced as key proteins (hub) in cirrhosis." (PMID 33585012, 2020). "Centrality and cluster screening identified hub genes, including APOE, TTR, CLU, and APOA1 in cirrhosis." (PMID 28224023, 2016). "Among the genes that involved in cirrhosis, APOE determined as seed while genes of HCC have no seed." (PMID 28224023, 2016).